IGF1 (insulin like growth factor 1)
Diseases named in the same sentence as IGF1 in open-access papers (continued):
Sharing a sentence is not in itself a finding about the gene and the disease.
acne (continued). "In analogy to acne, increased IGF-1/PI3K/AKT/mTORC1 signaling plays a key role in prostate morphogenesis and cancerogenesis." (PMID 33803410, 2021). "In regards to acne, this pathway has potential to exacerbate sebocyte activity and inflammation via insulin-mediated elevation of androgen and IGF-1 activities." (PMID 34207527, 2021). "The recent viewpoint on the pathogenesis of acne underlines that a western diet (WD) characterized by hyperglycemic carbohydrates and dairy protein consumption increases the insulin/IGF-1 signaling, thereby promoting acne." (PMID 34418600, 2021). "With that being said, PI3K⁄Akt activity is not only increased by FGFs but also by other growth factors such as insulin and IGF-1, thus offering a plausible explanation why individuals with metabolic syndrome suffer a more severe onset of acne." (PMID 34829964, 2021). "The pathogenesis of acne involves several hormonal pathways, including androgens, insulin-like growth factor 1(IGF-1), estrogens, and corticosteroids." (PMID 34207527, 2021). "In a previous study, serum IGF-1 levels showed a positive correlation with mean facial sebum excretion in post-adolescent patients with acne." (PMID 33255783, 2020). "IGF-1 and Cutibacterium acnes are the most important factors that induce an inflammatory response in acne." (PMID 31951642, 2020). "A recent study of biopsy samples from acne subjects showed that expression of pro-inflammatory cytokines is upregulated after stimulation of IGF-1." (PMID 31951642, 2020). "Insulin-like growth factor-1 (IGF-1) signaling is one of the most critical pathways in acne development, which is sufficient to induce pro-inflammatory cytokine (IL-1β, IL-6, IL-8, TNF-α) and MMPs expression in human sebocytes." (PMID 31979308, 2020). "Last, DHEAS, DHT and insulin-like growth factor-1 (IGF-1) serum levels correlate positively with acne lesion counts in female acne." (PMID 32586344, 2020). "Previously, clinical investigations have linked low insulin sensitivity and high glycemic load diet, which can augment insulin/insulin-like growth factor-1 (IGF-1) signaling, with the pathogenesis of acne." (PMID 34466486, 2019). "IGF-1 has been suggested as the pivotal driver of acne and stimulates follicular epithelial growth and keratinization." (PMID 30096883, 2018). "IGF-1 gene polymorphism has been shown to increase susceptibility to acne and IGF-1 plasma levels correlate with acne severity." (PMID 30096883, 2018). "Increased IGF-1 signalling in acne suppresses nuclear FoxO1, which is a nuclear co-suppressor of AR, and thus increases AR-mediated target gene expression." (PMID 28927457, 2017). "Recent evidence underlines that dietary factors, especially hyperglycaemic carbohydrates and milk consumption, increase insulin/IGF-1 signalling promoting acne." (PMID 28927457, 2017). "The expression of IGF-1, the most important pro-survival stimulus and mitogen of SGs, was increased in the basal and suprabasal layers of SGs of acne patients." (PMID 28927457, 2017). "We have to appreciate that acne is a pro-survival disease of the sebaceous follicle with increased IGF-1/AKT/mTORC1-survivin signalling." (PMID 28927457, 2017). "Increased insulin-IGF-1 signaling in acne vulgaris activates PI3K-Akt-mTORC1 signaling cascade and plays a key role in the Western-diet induced acne." (PMID 28036057, 2016). "Placebo-controlled studies have demonstrated that high glycaemic load diets aggravate acne, result in postprandial hyperinsulinaemia and increase serum levels of free IGF-1 19–27." (PMID 23614736, 2013). "On the other hand, seborrhea, acne, T2D and cancer are frequently observed in acromegaly with increased GH/IGF-1 signaling in comparison to healthy controls." (PMID 21699736, 2011).
acne (continued). "High glycemic load diets have been recognized as aggravating factors of acne, whereas a low glycemic load diet improved acne and decreased the bioavailability of free IGF-1 in plasma." (PMID 21699736, 2011). "IGF‐1 is upregulated in puberty and has been shown to be highly abundant in acne‐affected skin." (PMID 39927601, 2025). "Further, congenital deficiencies of IGF‐1 resulted in an absence of acne, unless there was IGF‐1 supplementation." (PMID 39927601, 2025). "In acne, IGF-1 signaling promotes sebaceous lipogenesis and inflammatory drive." (PMID 41614884, 2025). "Notably, the induction of IGFBP-3 points to the modulation of the IGF-1 pathway, offering a possible mechanistic basis for anti-acne benefits that extend beyond sebum reduction alone." (PMID 41614884, 2025). "Moreover, insulin-like growth factor 1 modulates elevated lipid production and heightened androgen receptor activity, hence exacerbating the inflammatory potential in acne." (PMID 40006023, 2025). "Such trials should use harmonized severity measures and incorporate mechanistic endpoints—such as microbiome profiling, inflammatory biomarkers, and IGF-1/mTOR signaling assays—to clarify the pathways through which probiotics may influence acne." (PMID 41470154, 2025). "IGF-1 modulators have been reported to be effective treatments for acne." (PMID 38585341, 2024). "Interestingly, our data suggest a trend towards lower mean ω-3 FA levels and higher mean IGF-1 levels in acne patients." (PMID 38672789, 2024). "Acne is a common inflammatory condition characterized by comedones, papules, and pustules, often resulting from increased sebum production influenced by hormones such as insulin-like growth factor-1 and androgens." (PMID 39445245, 2024). "IGF-1 stimulates the adrenal and gonadal glands to synthesize androgens, which in turn stimulate sebum production, contributing to the development and persistence of acne." (PMID 39445245, 2024). "Studies have shown that elevated serum levels of IGF-1 are positively correlated with the number of acne lesions in women, and lowering IGF-1 levels may prevent the development of acne." (PMID 38585341, 2024). "The enhanced generation of IGF-1 as a result of protein consumption coincides with excessive IGF-1 signalling during puberty, which explains the sooner initiation of puberty and the maintenance of acne in the third decade of age among people ingesting that drink." (PMID 38794714, 2024). "Future studies should investigate whether IGF-1 levels could be used as a screening tool to assess dairy intake in acne patients." (PMID 37892480, 2023). "The mean plasma IGF-1 level was significantly higher in acne cases than in non-acne controls, suggesting that IGF-1 may play a role in the development of acne." (PMID 38202116, 2023). "Individuals with Laron syndrome, who exhibit a congenital IGF-1 deficiency, are of short stature and never develop acne unless therapeutically substituted with recombinant IGF-1." (PMID 37998335, 2023). "Above all, these results illuminated that emodin inhibits the activation of the PI3K/Akt/FoxO1 pathway in human sebocytes, suggesting that emodin may stagnate acne formation by inhibiting IGF-1-induced lipogenesis." (PMID 38062074, 2023). "For acne patients, avoiding dairy products may be beneficial, particularly regarding the casein content in cow’s milk, which increases the IGF-1." (PMID 37174421, 2023). "What is already clear is that insulin serum levels have been observed to be elevated in patients with acne vulgaris, and that both acne and IR share the hormonal and signal transduction pathways, including insulin-like growth factor-1 (IGF-1) and the mammalian target of rapamycin kinase 1 (mTORC1)." (PMID 37626790, 2023). "In contrast, individuals with Laron syndrome exhibiting severe congenital IGF-1 deficiency do not develop acne vulgaris and are of small stature." (PMID 36729355, 2023).
acne (continued). "By contrast, a high-glycemic diet and excessive dairy product intake may activate insulin/IGF-1 signaling, stimulating mTORC1 and enhancing keratinocyte proliferation, and hormone production, leading to acne vulgaris." (PMID 35966699, 2022). "In addition, insulin-like growth factor 1 (IGF1) plays an important role in the pathogenesis of acne by inducing sebum overproduction." (PMID 35800343, 2022). "The relationship between IGF1 and acne remains controversial." (PMID 35800343, 2022). "Even so, acne does not develop when there is loss of functionality of the androgen receptor, but IGF-1 is the main hormone that controls pubertal development, and decreases after this phase." (PMID 35889022, 2022). "These issues focus on IGF-1 as a key molecule in the onset and development of acne." (PMID 35889022, 2022). "In summary, differential spatial FA distributions in facial sebum and correlation with those in erythrocytes and IGF1 levels in serum may shed some light on the pathology of acne in male and female adults." (PMID 35800343, 2022). "Raised blood glucose values are associated with acne patients principally because an increase in blood glucose levels triggers insulin secretion, which decreases the binding protein for IGF-1, promoting cell proliferation by IGF-1." (PMID 35677010, 2022). "The free IGF-1, a potent mitogen, promotes acne development by upregulating hyperkeratinization." (PMID 36678524, 2022). "They suggest that IGF1 might participate in the pathogenesis of acne by increasing expression of inflammatory biomarkers and sebum production in sebocytes." (PMID 36439142, 2022). "Hence, our findings suggest that BV and melittin inactivate IGF-1R/Akt/mTOR/SREBP and this is likely to be important in the anti-lipogenic action against C. acnes or IGF-1, offering therapeutic strategies to target lipogenesis in acne." (PMID 35328573, 2022). "In addition, we observed distinct patterns of correlations between Omega-3 PUFA in erythrocytes and sebum and correlations between IGF1 levels in serum and sebum in male acne patients." (PMID 35800343, 2022). "Indeed, as described, EDCs interfere with several key endogenous hormonal pathways that are common to acne, including those mediated by androgens, estrogens, IGF-1, and CRH/cortisol." (PMID 34207527, 2021). "IGF-1 increases androgen sensitivity and activates sebaceous gland activity; thus, it is possible that BPA may exacerbate acne by enhancing the ratio of androgen-to-estrogen production and facilitating androgen sensitivity via IGF-1 signaling." (PMID 34207527, 2021). "Many studies have described the mitigation of inflammatory acne with a low glycemic, plant-rich diet, and it has been proposed that the therapeutic effects of diet were mediated via alterations in PPARy, IGF-1, and androgen-signaling." (PMID 34207527, 2021). "Furthermore, GH stimulates the production of IGFs, and, in particular, women evidencing acne lesions have higher levels of IGF-1, compared with androgens, sebaceous gland growth, and lipogenesis." (PMID 34834345, 2021). "Furthermore, an increase in sebum levels in acne patients was found to be related to an increased concentration of sebum insulin-like growth factor-1 (IGF-1)." (PMID 34521361, 2021). "A link between IGF-1 and acne is suggested by the known cross-talk between IGFs and androgens, which are implicated in acne pathogenesis, and by absence of acne in Laron dwarfs and the appearance of acne upon IGF-1 treatment." (PMID 31416218, 2019). "A typical Western pattern diet which includes foods with complex mixture of fat (i.e., red meat), high glycemic index, and dairy may aggravate acne by raising the levels of insulin-like growth factor-1 (IGF-1) and insulin." (PMID 31284694, 2019). "IGF-1-deficient patients with Laron syndrome do not develop acne and other mTORC1-driven diseases of civilization." (PMID 28927457, 2017). "Intriguingly, serum IGF-1 levels of acne patients significantly correlate with survivin expression." (PMID 28927457, 2017).
acne (continued). "Activated IGF-1/mTORC1 signalling promotes the expression of the anti-apoptotic protein survivin, which has recently been found to be upregulated in the skin of acne patients." (PMID 28927457, 2017). "Increased IGF-1 signalling of puberty superimposed with insulin signalling of Western diet (hyperglycaemic carbohydrates and milk) provide the input signals for disturbed acne metabolomics including mTORC1-S6K1-mediated insulin resistance." (PMID 28927457, 2017). "Moreover, milk and dairy products act as enhancers of insulin/IGF-1 signalling, supporting sebaceous lipogenesis and acne aggravation through the derepression of the androgen receptor." (PMID 25977937, 2015). "Indeed, IGF-1 is the growth promoter of puberty, playing a central role in acne and the induction of hyperandrogenism as highlighted by the fact that IGF-1-overtreated Laron patients usually exhibit hyperandrogenism." (PMID 25977937, 2015). "The underlying mechanism of dietary effect on acne vulgaris formation might be the role of insulin-like growth factor-1 (IGF-1) in facilitating cell proliferation involved in acne vulgaris pathogenesis." (PMID 22898209, 2012). "It was hypothesized that increased intestinal permeability occurred in acne vulgaris patients, thus enhancing IGF-1 absorption in the gut." (PMID 22898209, 2012). "Indeed, the highest incidence of acne occurs when IGF-1 levels peak and adult women with acne have high levels of IGF-1." (PMID 22253996, 2010). "It is worth noting that the findings obtained in this study is consistent with the mechanistic hypothesis of CleodermTM; however, studies evaluating the measurement and activity of IGF-1 and other pathways related to acne in in vitro sebocyte models and lipogenesis assays should be conducted." (PMID 41614884, 2025). "Based on the results of research, IGF-1 related to insulin and a specific inhibitor of Smad3, and IL-17 antibodies related to inflammatory pathways, are expected to become targets for the prevention and treatment of acne-induced PSs, providing potential directions for new drug development." (PMID 38585341, 2024). "C. acnes plays a pivotal role in acne pathogenesis by interacting with innate immunity through the release of extracellular enzymes and reactive oxygen species and the activation of TLRs, alongside influencing sebum production, keratin, filaggrin, and IGF-1 levels." (PMID 38791344, 2024). "In milk and its derivatives, insulin-like growth factor 1 (IGF-1) is present, a molecule related to the stimulation of the growth and division of epidermal cells, the creation of sebum, and the elevation of estrogen factors, all of which contribute to the development of acne." (PMID 38633058, 2024). "Therefore, pharmacological attenuation of IGF-1-mediated intracellular transduction may hold promise for the therapeutic management of acne." (PMID 39349732, 2024). "Furthermore, and especially in regard to acne, they may reduce levels of insulin-like growth factor (IGF)-1, the central nutrient inducer of acne." (PMID 38672789, 2024). "Additionally, consuming whole and skimmed cow’s milk may worsen acne since it includes more hormones or other bioactive molecules (α-lactalbumin, growth factor-stimulating hormones, steroids, IGF-1, etc.)." (PMID 37174421, 2023). "Acne vulgaris may be induced in the course of disorders that are characterized by abnormal levels, not only of androgens, estrogens, and progesterone but also of insulin and insulin-like growth factor-1." (PMID 37626790, 2023). "Thus, emodin may counteract the pro-acne effects of IGF-1 by inhibiting the phosphorylation of PI3K/Akt/FoxO1 pathway, thereby downregulating the expression of lipogenic factors." (PMID 38062074, 2023).
acne (continued). "Therefore, this study aimed to investigate the beneficial function and efficiency of a therapeutic strategy based on a synthetic SREBP/PPAR decoy ODN in the simultaneous regulation of the transcription factors SREBP-1 and PPAR-γ in C. acnes- and IGF-1-induced acne vulgaris models." (PMID 36551286, 2022). "Furthermore, mTOR, FoxO1, and serum IGF-1 along with a high-glycemic-load diet may be involved in the development of acne." (PMID 35163615, 2022). "Thus, as people age and drink less milk, they may be less exposed to IGF1 and, therefore, also less prone to the development of acne." (PMID 30096803, 2018). "In this study, the IGF-1-induced expression of PPAR-γ in sebocytes was diminished by K. parviflora extract, postulating that K. parviflora extract could be developed as an anti-acne agent with a sebostatic effect associated with the inactivation of PPAR-γ." (PMID 30400322, 2018). "Thus, increased IGF-1-AKT signalling in acne via FoxO3a suppression may favour c-Myc-driven SG differentiation." (PMID 28927457, 2017). "IGF-1 may thus promote infundibular keratinocyte proliferation (comedogenesis) in acne." (PMID 28927457, 2017). "Moreover, IGF-1 is able to stimulate 5α reductase, adrenal and gonadal androgen synthesis, androgen receptor signal transduction, sebocyte proliferation, sebum production, and lipogenesis, affecting acne development." (PMID 25977937, 2015). "Indeed, patients with Laron syndrome, which is a congenital IGF-1 deficiency caused by a growth hormone receptor mutation, never present with acne unless they are treated." (PMID 26413187, 2014). "Endocrine factors involved in acne may be affected by milk consumption because milk is an insulinotropic nutrient and has a high insulinemic index which would increase serum insulin and IGF-1 levels." (PMID 22898209, 2012). "For example, cathelicidin LL-37 plays a critical role in rosacea by driving inflammation, vascular reactivity, and tissue damage, while the IGF-1/IGFBP axis regulates sebaceous lipogenesis and keratinocyte proliferation in acne pathophysiology." (PMID 41614884, 2025). "The association between acne and milk, but not fermented milk products, may be attributed to the ability of probiotic bacteria, particularly lactobacilli, to reduce the levels of IGF‐1 during fermentation when they are added to milk." (PMID 40013532, 2025). "The levels of androgens (such as testosterone), IGF-1, sex hormone-binding globulin (SHBG), and other important hormones in acne patients are measured and analysed using hormonal assays." (PMID 38384651, 2024). "Substantial evidence indicates that IGF-1 stimulates sebum production in SZ95 sebaceous gland cells, with a concomitant positive correlation between IGF-1 levels and clinical acne severity." (PMID 38915336, 2024). "However, for acne-induced PS formation, focusing on the target of IGF-1 may achieve better results." (PMID 38585341, 2024). "Among them, IGF-1, IGF-1R and downstream mechanistic target of rapamycin (mTOR) play key roles in the development of acne and the formation of acne-induced PSs." (PMID 38585341, 2024). "Oral administration of Lactobacillus can reduce insulin-like growth factor 1 (IGF-1) and increase forkhead box protein O1 (FoxO1) expression in the skin, improving the condition of acne." (PMID 37828993, 2023). "In acne patients, a correlation between the serum levels of IGF-1, DHEA-S, and dehydroepiandrosterone, as well as the number of acne lesions and sebum production, has also been reported." (PMID 36694512, 2022). "In this study, we demonstrated that IGF1 levels were positively correlated with SFA and MUFA levels in sebum from male patients with moderate acne." (PMID 35800343, 2022). "In contrast, BV and melttin 100 ng·mL−1 and 1 μg·mL−1, respectively, suppress the inflammatory response induced by IGF-1 in SZ95 sebocytes, a well-established in vitro model of pro-inflammatory acne." (PMID 35328573, 2022).